ARID5B (AT-rich interaction domain 5B)
Diseases named in the same sentence as ARID5B in open-access papers (continued):
Sharing a sentence is not in itself a finding about the gene and the disease.
breast cancer (4 papers, 2021 to 2023). A primary or metastatic malignant neoplasm involving the breast. "Maybe the results indicated mRNA and protein level expression of ARID5B are functionally demarcative in breast cancer." (PMID 33592583, 2021). "IPA showed that the pathways of mammary tumours, genitourinary tumours and extracranial solid tumours were strongly activated in G1 cells, in which AREG, ARL4C, and ARID5B showed the greatest contribution to activation." (PMID 35184420, 2022). "Low mRNA expression of ARID5B (p=0.045) and JARID1D (p=0.0209) was interrelated with worse OS in grade I breast cancer." (PMID 33592583, 2021). "Low mRNA expression of ARID1A (p=0.0096), ARID2 (p=0.0066), ARID3B (p= 0.000024), ARID5A (p=0.0435), ARID5B (p=0.0022), JARID1A (p=0.0044), JARID2 (p=0.0463) were interrelated with worse OS in grade III breast cancer patients." (PMID 33592583, 2021). "The low mRNA expression of ARID1B (p=0.0023), ARID2 (p=0.0439), ARID4A (p=0.0056), ARID4B (p=0.0317), ARID5B (p=0.00054), JARID1D (p=0.043), JARID2 (p=0.0068) were interrelated with poor survival in breast cancer patients with negative lymph node." (PMID 33592583, 2021).
endometrial carcinoma (3 papers, 2016 to 2025). A malignant tumor arising from the epithelium that lines the cavity of the uterine body. "ARID5B classified in the SWI/SNF complex family is less mutated in the high-copy-number subtype of endometrial carcinoma." (PMID 27340867, 2016).
gastric cancer (3 papers, 2020 to 2022). A primary or metastatic malignant neoplasm involving the stomach. "Other than this, ARID5B has also been reported to associate with the ontogeny and evolution of gastric cancer (GC) and prostate cancer (PCa)." (PMID 32595701, 2020).
rheumatoid arthritis (3 papers, 2013 to 2024). A chronic, systemic autoimmune disorder characterized by inflammation in the synovial membranes and articular surfaces. "Another Arid family transcription factor, Arid5b, has also been proposed as a risk factor for rheumatoid arthritis." (PMID 32079226, 2020). "In Japanese studies, this SNP, located within the ARID5B gene, has been associated with rheumatoid arthritis and Graves’ disease." (PMID 24168730, 2013). "However, several studies have demonstrated the involvement of transcription factors expressed in chondrocytes, such as AT-rich interactive domain 5a (Arid5a), Arid5b, and IκBζ, in rheumatoid arthritis." (PMID 32079226, 2020).
cervical cancer (2 papers, 2017 to 2020). A primary or metastatic malignant neoplasm involving the cervix. "A recent study comparing genetic-and-epigenetic cell cycle networks (GECNs) of embryonic stem cells (ESCs) and cervical cancer cells showed that ARID5B was one of the eight cell cycle genes whose methylation patterns significantly differ between ESCs and HeLa cells." (PMID 32595701, 2020). "The methylation of ARID5B could focus on the specific cell cycle genes of cervical cancer cells and would have minimal side-effects on the shared core genes and thus provide greater therapeutic benefits." (PMID 32595701, 2020). "Chromatin remodeling genes ARID1A and ARID5B, WNT signaling regulator CTNNB1, and the negative regulator of PI3K signaling PTEN, were among the notable genes significantly more mutated in HPV-inactive cervical cancers." (PMID 28077784, 2017).
chronic lymphocytic leukemia (2 papers, 2020 to 2025). "Moreover, ARID5B has been revealed to be involved in fludarabine-refractory of chronic lymphocytic leukemia (CLL) patients." (PMID 32595701, 2020).
colon carcinoma (2 papers, 2007 to 2020). "APC, SMAD4, NF1 (neurofibromin 1), ARID5B, NCOR1 (nuclear receptor corepressor 1), IGFR1R (insulin like growth factor 1 receptor) and GNAS (GNAS complex locus) were the most often mutated genes in patient-derived colon cancer cells." (PMID 33050525, 2020). "APC, SMAD4 (SMAD family member 4), NF1 (neurofibromin 1), ARID5B, NCOR1 (nuclear receptor co-repressor 1), IGFR1R (insulin like growth factor 1 receptor) and GNAS (GNAS complex locus) were the most often mutated genes in patient-derived colon cancer cells, YUMC-C1 and YUMC-C2." (PMID 33050525, 2020).
acute leukemia (1 paper, 2014). A clonal (malignant) hematopoietic disorder with an acute onset, affecting the bone marrow and the peripheral blood. "Because the variant ARID5B rs10821936 allele was remarkably associated with an increased risk of MLL-r acute leukemia, we tested whether this risk allele was associated to a specific MLL TPG or to any of the frequent MLL breakpoint regions." (PMID 24564228, 2014).
adenoma (1 paper, 2023). A neoplasm arising from the epithelium. "SOX9 and ARID5B were mutated in the adenoma group but not in the cancer group." (PMID 37546388, 2023).
Alzheimer disease (1 paper, 2021). A progressive, neurodegenerative disease characterized by loss of function and death of nerve cells in several areas of the brain leading to loss of cognitive function such as memory and language. "Differential methylation of a six-probe region spanning 99 base pairs within ARID5B gene has also been reported in Alzheimer’s disease." (PMID 33933144, 2021).
benign prostate hyperplasia (1 paper, 2020). "The dysregulation of ARID5B has also been evidenced to play a part in the regulatory pathways of PCa by comparing the proteins of PCa and benign prostate hyperplasia (BPH) tissue." (PMID 32595701, 2020).
bladder urothelial carcinoma (1 paper, 2024). "Additionally, mutations in ARID1A were frequent in bladder urothelial carcinoma (BLCA), UCEC, LUAD, and lung squamous cell carcinoma (LUSC), while ARID5B mutations were prevalent in UCEC (10%)." (PMID 38920700, 2024).
breast tumors (1 paper, 2016). "This is the case of GATA3 in breast tumors, ZNF292 in low grade gliomas, ARID5B in uterine carcinomas, and MYC in diffuse B-cell lymphomas." (PMID 26792175, 2016).
chordoma (1 paper, 2025). Chordomas are rare malignant tumors arising from embryonic remnants of the notochord in axial skeleton. "Specific mutations, such as MRE11 (p < 0.01) and ARID5B (p < 0.05), were significantly enriched in pediatric chordoma compared to adults, highlighting potential age-specific genetic differences in chordoma." (PMID 39941902, 2025).
colorectal adenoma (1 paper, 2023). An adenoma that arises from the colon or rectum.
colorectal cancer (1 paper, 2023). A primary or metastatic malignant neoplasm that affects the colon or rectum. "We surmise that ARID5B might be a new target for the prevention of colorectal cancer." (PMID 37546388, 2023).
coronary artery disease (1 paper, 2021). "It has been previously demonstrated that ARID5B has a regulatory role in the phenotypic change of smooth muscle cells and SNPs within ARID5B have been linked to T2DM and coronary artery disease." (PMID 33933144, 2021).
COVID-19 (1 paper, 2025). A disease caused by infection with severe acute respiratory syndrome coronavirus 2. "The hypermethylated genes with the lowest p values for hospitalized COVID-19 patients at inclusion (T1) vs. at 6 weeks post-inclusion (T2) were PARP9, ABCA1, MX1, OAS1, ARID5B, and the hypomethylated genes included TMEM131, ROCK1, IFNGR1, CFAP61, VRK2, and C6orf138." (PMID 41227320, 2025).
deafness (1 paper, 2023). An inherited or acquired condition characterized by the complete loss of the ability to hear from one or both ears. "Some of them (e.g., ARID5B, CTBP2, and FTO) were previously identified as causal loci of Mendelian forms of deafness." (PMID 37165447, 2023).
desmoid fibromatosis (1 paper, 2022). "An ARID5B p.K348E pathogenic variant was detected in the desmoid fibromatosis." (PMID 35978432, 2022).
endometrioid tumor (1 paper, 2022). A benign, borderline, or malignant epithelial tumor of the female reproductive system characterized by the presence of glands and/or cysts lined by neoplastic cells that resemble endometrial cells.
epilepsy (1 paper, 2026). A brain disorder characterized by episodes of abnormally increased neuronal discharge resulting in transient episodes of sensory or motor neurological dysfunction, or psychic dysfunction. "Interestingly, a previous study in patients suggested a potential association of Arid5b with epilepsy 46, suggesting that Arid5b may be a direct target of WDR5-H3K4me3 under epileptic conditions." (PMID 41510154, 2026). "To elucidate the role of ARID5B in epilepsy, we first investigated whether ARID5B protein expression is altered." (PMID 41510154, 2026). "Overall, our study reveals a novel mechanism whereby H3K4me3-mediated epigenetic information is translated into altered inhibitory synaptic protein expression via ARID5B, thereby expanding our understanding of how the "histone code" orchestrates neural circuit regulation in epilepsy pathogenesis." (PMID 41510154, 2026).
hearing loss (1 paper, 2021). "It is therefore possible that the association of MYO3B, ARID5B and ZNF318 with tinnitus is secondary to their role in hearing since tinnitus is usually manifested when there is a hearing loss present." (PMID 33742053, 2021).
HIV-1 infection (1 paper, 2024). The type species of lentivirus and the etiologic agent of acquired immunodeficiency syndrome (AIDS). "The ex vivo frequency of adaptive NK cells correlated positively with ARID5B levels of expression, showing greater expansions of adaptive NK cells in HIV-1 infection, relative to controls." (PMID 38385747, 2024). "Our findings, therefore, suggest that mitochondrial structural disorganization rather than a decreased expression of ARID5B could affect the performance of the ETC and metabolic adaptation of NK cells in HIV-1 infection." (PMID 38385747, 2024).
Hypertension (1 paper, 2017). The presence of chronic increased pressure in the systemic arterial system. "The effect sizes of ARID5B gene expression and methylation levels associating with carotid plaque score are higher than the effect sizes of T2DM (1% of variability) or hypertension (0.9%) in the same model." (PMID 28855511, 2017).
promyelocytic leukemia (1 paper, 2014). "The gene expression level of ARID5B is up-regulated in two different AML subtypes (acute megakaryoblastic and promyelocytic leukemia)." (PMID 24564228, 2014).
steatosis (1 paper, 2019). Increased lipid within the cytoplasm of cells. "Phf2-overexpressing mice develop steatosis, and Arid5b knockout mice are resistant to high fat diet-induced weight gain and obesity." (PMID 31882756, 2019).
tumor (21 papers, 2015 to 2025). "We pooled all 20 genes (Stx6, Ramp1, Traf3ip1, Nckap5, Pfkfb2, Trmt1l, Rprd1b, Rer1, Sepsecs, Rhobtb1, Tsen15, Abcc3, Arid5b, Tnr, Dock2, Tti1, Fam81a, Oxr1, Plxna2 and Tbc1d31) together as the mouse tumour susceptibility gene signature (mTSGS)." (PMID 39067134, 2024). "Multivariate linear regression analysis identified SNPs in 11 genes (Sepsecs, Rhobtb1, Tsen15, Abcc3, Arid5b, Tnr, Dock2, Tti1, Fam81a, Stx6, and Oxr1) that were independently associated with the tumour multiplicities." (PMID 39067134, 2024). "A study also showed that forced expression of ARID5B in immature thymocytes causes thymus retention, differentiation arrest, radioresistance, and tumor development in zebrafish." (PMID 36559013, 2022). "Next-generation sequencing (NGS) and fluorescence-activated cell sorting (FACS) analysis confirmed that the mutational landscape and HLA-I haplotype of the PDX matched the patient’s primary tumor except for a subclonal ARID5B mutation." (PMID 35484264, 2022). "Dysfunctions of ARID5B may facilitate tumorigenesis, which has been proved by high-throughput screenings for inherited predispositions or tumor genomic mutations." (PMID 41488748, 2025). "ARID5B encodes a transcription co-activator that has been shown to induce smooth muscle cell differentiation and reduced cell proliferation, and its mutation may have contributed to the pathogenesis of the tumor." (PMID 35978432, 2022). "The gatekeeping role of ARID5B is supported by a bioinformatics study ranking ARID5B as one of the top tumor suppressor genes." (PMID 37483604, 2023). "Like ARID5A, mRNA expression of ARID5B was interrelated with better survival in our study, which indicated the function of a tumor suppressor." (PMID 33592583, 2021). "In contrast genes involved in development and differentiation (Arid5b, Inmt, Grem2, Gdap10), cell metabolism (Alas1, Gsta1, Thrsp, Fdft1, Elovl6), tumor growth (SerpinA4, Cish, Rpl36), and cell cycle control (PLK3, Myc, HNF6/Onecut1) were downregulated." (PMID 33004985, 2020). "To validate SMART-ddPCR measurements of AI using a second method, we carried out Sanger sequencing across the IKZF1 and ARID5B SNPs for constitutional and tumor DNA from SNP heterozygotes." (PMID 26575185, 2015). "Multivariate analyses flagged SNPs in 20 genes (Stx6, Ramp1, Traf3ip1, Nckap5, Pfkfb2, Trmt1l, Rprd1b, Rer1, Sepsecs, Rhobtb1, Tsen15, Abcc3, Arid5b, Tnr, Dock2, Tti1, Fam81a, Oxr1, Plxna2, and Tbc1d31) independently tied to various tumour characteristics, designated as a mTSGS." (PMID 39067134, 2024). "Furthermore, decreased ARID5B expression was observed in tumor cells from B-ALL patients when compared to B cells from non-leukemic individuals." (PMID 37483604, 2023). "While there is a slightly higher tumor mutational burden in EPAS1-altered tumors (9.9 vs. 4.9 mut/Mb), they are enriched in and associated with genes promoting immune evasion, including ARID5B, SPINT1, AAK1, CLIC3, SORT1, SASH1, and FGFR3, respectively (q < 0.001)." (PMID 36421334, 2022). "ATP2A2 and ARID5B correlated with the GH change rate in the octreotide loading test, and WWC3, SERINC1, and ZFAND3 correlated with the tumor volume change rate after somatostatin analog treatment." (PMID 36435867, 2022). "ARID5B, BAZ2B, RABGAP1, SFRP2, and WBP1L have not been previously associated with MS risk, and all are associated with neoplastic diseases and cellular proliferation." (PMID 36685876, 2022). "ATP2A2 and ARID5B were identified as being correlated with the GH change rate in response to octreotide treatment, and WWC3, SERINC1, and ZFAND3 were identified as being correlated with the tumor volume change rate in response to SSA treatment." (PMID 36435867, 2022). "ARID5B had significant positive correlations with stromal and immune scores in PAAD, revealing that this gene might effectively function in the tumour microenvironment." (PMID 35127746, 2021).
tumor (continued). "The mRNA expression of ARID3A, ARID3B, ARID4B, JARID1B, JARID1C, JARID2 in tumor tissues was more expressive in normal tissues, ARID1B, ARID3C, ARID4A, ARID5A, ARID5B, JARID1A mRNA expression in tumor tissues were lower than that in the normal tissues (p<0.05)." (PMID 33592583, 2021). "For the HeH-associated SNPs in CEBPE, ARID5B, and PIP4K2A, we did not see significant preferential gain of risk alleles in tumor samples from heterozygous patients." (PMID 26575185, 2015). "Conversely, a negative correlation between ARID5A/ARID5B and tumor purity was found." (PMID 36034939, 2022).
cancer (17 papers, 2017 to 2025). A tumor composed of atypical neoplastic, often pleomorphic cells that invade other tissues. "Expression of ARID5B was negatively correlated with the cancer susceptibility signal in this region." (PMID 36199081, 2022). "In addition, pan-cancer patients harboring ARID5B mutations also had higher TMB values (mean TMB score: 47.3 versus 11.0, P < .0001)." (PMID 35239432, 2022). "Notable downregulated genes included Mki67, Ccn1, Muc1, Atf3, Ntrk2, Arid5b, Igf1r, Igf2bp2, Cd47, and Cd37 (oncogenic function) and integrin-related genes, Itga7, Itga11, Itgam and Notch1 (cancer stem cell markers)." (PMID 39946195, 2025). "The more novel findings in this study were in genes (ARID5B, BAZ2B, RABGAP1, SFRP2, and WBP1L) that are associated with cancer risk and cellular differentiation." (PMID 36685876, 2022). "Genetic alterations in ARID1A (12%), ARID1B (5%), ARID2 (6%) and ARID5B (2.6%) were identified in multiple cancer types." (PMID 35239432, 2022). "Prognostic variants were identified in or near MSH6, POLQ, ARID5B, and IDH2, which are previously reported cancer driver genes." (PMID 32066500, 2020). "The variants in cancer driver genes, MSH6, POLQ, ARID5B, and IDH2, warrant further study to determine the mechanism by which these variant affect cancer progression." (PMID 32066500, 2020). "Other variables, such as ARID5B mutation status, age, sex and metastatic status of patients when the administration of ICIs was initiated, did not demonstrate satisfactory efficiency in predicting the prognosis of ICI therapy through pan-cancer analysis." (PMID 35239432, 2022). "Colocalization analyses, within a 500-kb region of the risk SNP, with ezQTL detected a negative correlation between ARID5B expression in whole blood and effects on cancer risk." (PMID 36199081, 2022). "Interestingly, our panel included genes already described to be cancer predisposition genes (FAS, ITK, KIF1B, PGR and MET) or previously reported as playing important roles in cancer (ABI1, ARID5B, DNMT3A, HEY1, KDM5C, NCOA1, NUP98, and SLC34A2), or in DNA repair process (FANCF)." (PMID 30925779, 2019). "Five of these genes (ARID5B, BAZ2B, RABGAP1, SFRP2, WBP1L) are associated with cancer risk and cellular differentiation and have not been previously identified in MS studies." (PMID 36685876, 2022). "In addition, HLF and ARID5B were identified as TFs of Tregs in precancer stages (e.g., N_HPV, AAH, NEOLP, EOLP), while regulons such as FOXO1 and STAT5B were specifically detected in cancers (e.g., IDC, AIS, MIAC, IAC and PDAC)." (PMID 38645221, 2024).
cardiovascular disease (2 papers, 2017 to 2024). "Mediation analysis supports assumptions that ARID5B expression mediates effects of cg25953130 methylation and several cardiovascular disease risk factors on atherosclerotic burden." (PMID 28855511, 2017). "Moreover, ARID5B is upregulated in an in vitro monocyte model mimicked APS and in monocytes from patients with cardiovascular disease, and is critical for the inflammatory response in lipopolysaccharide (LPS)‐stimulated macrophages." (PMID 38224186, 2024).
digestive tumours (1 paper, 2021). "Correlations between ARID5B and C6 infiltrates indicated that digestive tumours expressing ARID5B tended to be enriched with TGF-β." (PMID 35127746, 2021).
ARID5B also shares sentences with these, for which no sentence is quoted: acute myeloid leukaemia (2 papers); hypothyroidism (2); Insulin resistance (2); autoimmune thyroid disease (1); BAFopathy (1); basal cell carcinoma (1); Chronic Myeloid Leukemia (1); Cirrhosis (1); cryptorchidism (1); endometrial endometrioid adenocarcinoma (1); fibrosis (1); glioblastoma (1); glioma (1); gout (1); Graves disease (1); head and neck cancer (1); hepatocellular adenoma (1); infection (1); Kabuki syndrome (1); keratoconus (1); kidney disease (1); liver cancer (1); liver fibrosis (1); metabolic disease (1); multiple sclerosis (1); oropharyngeal carcinoma (1); prostate carcinoma (1); sarcoma (1); Splenomegaly (1); Stroke (1).
A further 6 diseases each share a sentence with ARID5B in 1 paper.